ALB (albumin)
Diseases named in the same sentence as ALB in open-access papers (continued):
Sharing a sentence is not in itself a finding about the gene and the disease.
Cirrhosis (continued). "Patients with mild fibrosis (F1-F2 determined by histology) were significantly younger and had significantly higher levels of platelets and albumin compared to the patients with severe fibrosis and cirrhosis F3-F4." (PMID 31058108, 2019). "Four hundred forty patients with decompensated cirrhosis (uncomplicated ascites) received standard medical care or standard care plus albumin (40 g twice weekly for 2 weeks then weekly for up to 18 months)." (PMID 30873165, 2019). "This suppressive effect was mediated by increased plasma Prostaglandin E2 (PGE2) in acutely decompensated cirrhosis related to low levels of albumin, which regulates PGE2 bioavailability." (PMID 30873165, 2019). "The study implicated that patients with decompensated cirrhosis showed elevated levels of ALT, AST, and TBIL, but a reduction in ALB levels in comparison to healthy individuals." (PMID 30508917, 2018). "In comparison to those with AST ≤148 IU/L, those with AST> 148 IU/L were older, had higher necroinflammation scores, had higher ALT levels, had lower albumin levels, and included higher proportions of patients who had thrombocytopenia and cirrhosis." (PMID 29953518, 2018). "The independent predictive factors of cirrhosis development were serum bilirubin >17 μmol/L, serum albumin <38 g/L and moderate to severe lymphocytic interface hepatitis." (PMID 29593060, 2018). "Among patients with cirrhosis, age was negatively correlated with spleen size (r2 = −0.250, p < 0.001), hemoglobin (r2 = –0.166, p = 0.010), and albumin (r2 = –0.299, p < 0.001)." (PMID 30072589, 2018). "Poisson regression analysis revealed a significant relationship between number of units of RBC utilized and age, albumin, presence of cirrhosis, blood urea nitrogen, length of operation, and prothrombin time." (PMID 30487957, 2018). "Liver function is lost as cirrhosis progresses, thereby lowering the blood levels of ALB and glucose." (PMID 29321963, 2018). "The serum albumin level should be monitored to avoid misdiagnosis of cirrhosis in patients with NAFLD." (PMID 29177681, 2018). "Regarding albumin and total proteins, a marked decrease in the biosynthetic capacity of the hepatic parenchyma was observed in the cirrhosis and placebo groups (p<0.05)." (PMID 30643808, 2018). "Turning this paradigm around, the authors showed that treatment of five patients with acutely decompensated cirrhosis with 200 ml of 20% HSA increased serum albumin concentrations from 23 g/l to 30 g/l and reversed immunosuppression." (PMID 30155448, 2018). "In a systemic review of prognostic indicators in cirrhosis, serum albumin and bilirubin are the two most prominent individual prognostic variables.However, there are limited data on the prognostic information of ALBI score in cirrhotic patients." (PMID 30540824, 2018). "Patients with decompensated cirrhosis admitted to the hospital with a serum albumin of <30 g/L are eligible, subject to exclusion criteria." (PMID 30344180, 2018). "This randomised, controlled trial of 440 patients with cirrhosis and uncomplicated ascites compared standard diuretic therapy with standard diuretic therapy plus human albumin (40 g intravenously twice weekly in the first two weeks and then once weekly)." (PMID 30155448, 2018). "sAxl/albumin showed an acceptable accuracy for the detection of F≥2, F≥3, F4, and cirrhosis in comparison to ELFTM test as well as TE." (PMID 29072690, 2017). "Among the overall cohort, factors associated with increased HCC incidence were advancing age, presence of cirrhosis, high Child-Pugh score, low platelet count, low albumin, successful treatment with antiviral medications, and high sICAM-1." (PMID 28894136, 2017). "Since the BTR is a factor predicting prognosis, BCAA supplementation therapy was administered to cirrhosis patients to improve their serum albumin concentration." (PMID 29108327, 2017). "In conclusion, the sAxl/albumin ratio is suggested as an accurate biomarker of liver fibrosis and cirrhosis." (PMID 29072690, 2017).
Cirrhosis (continued). "In conclusion, sAxl/albumin ratio is an accurate marker of advanced liver fibrosis and cirrhosis in NAFLD and viral hepatitis." (PMID 29072690, 2017). "Chronic CCl4 mice had slightly elevated PGE2, normal plasma NO and albumin concentration and normal cardiac and renal function, similar to stable cirrhosis patients (Child Pugh A or low MELD score)." (PMID 26012885, 2016). "Patients with acutely decompensated cirrhosis admitted to hospital with a serum albumin of <30 g/L are eligible, subject to exclusion criteria." (PMID 26810999, 2016). "Due to the significant decreases in serum albumin levels seen in cirrhosis patients, the IMAT/albumin values were greatly increased in patients of Child-Pugh classes A and B comparing to that of the hepatitis patients." (PMID 28101103, 2016). "Independent predictors of survival included tumor size, number of lesions, tumor thromboses, cirrhosis, serum albumin level and serum total bilirubin level." (PMID 27387757, 2016). "We also found that tumor size, number of lesions, tumor thromboses, serum total bilirubin level; albumin and cirrhosis were the accurate independent predictors of OS." (PMID 27387757, 2016). "A progressive decline in serum albumin concentrations, rise in bilirubin and prolongation of the prothrombin time are characteristically observed as decompensated cirrhosis develops." (PMID 26563120, 2016). "We have now formed a Liver Index from the 4 liver parameters with the highest hazard ratios with respect to HCC aggressiveness, namely: blood total bilirubin, gamma glutamyl transpeptidase (GGTP), albumin and platelet levels (cirrhosis surrogate)." (PMID 28580457, 2016). "Albumin improves circulatory function in cirrhosis by expanding central blood volume and increasing cardiac output." (PMID 27144022, 2016). "In the later stage of cirrhosis, when albumin levels had shown significant decline, their fatty acid binding capacity was still in a compensation stage." (PMID 28101103, 2016). "We found that a composite Liver Score, comprising blood total bilirubin, GGTP, albumin and blood platelet levels (surrogate for cirrhosis) relate to both trends in the individual HCC aggressiveness components, and also to the Aggressiveness Index." (PMID 28580457, 2016). "Serum bilirubin, ALT, AST, and GGT levels were significantly higher, and serum albumin was significantly lower, in patients with cirrhosis." (PMID 26110613, 2015). "Albumin is routinely administered for patients with cirrhosis as part of current guidelines, however any albumin administered before ICU admission would affect the utility of albumin as a predictive measure of ICU outcome." (PMID 26462911, 2015). "In experimental cirrhosis of rats, albumin exerted a positive cardiac inotropic effect counteracting oxidative stress- and TNF-a-induced impairment of cardiac contractility." (PMID 26606982, 2015). "The first such demonstrated survival increase after albumin infusion was in patients with cirrhosis and spontaneous bacterial peritonitis (SBP) in 1999." (PMID 26606982, 2015). "Since the endogenous albumin of patients with decompensated cirrhosis is not only present at reduced levels, but also is functionally impaired, the many functions key to homeostasis that albumin performs are likely to be compromised." (PMID 26606982, 2015). "No patients had clinical, biochemical characteristics (including platelet count, serum liver enzymes, albumin and prothrombin time) or ultrasonographic findings suggestive of cirrhosis or portal hypertension (coarse liver texture or splenomegaly)." (PMID 26252899, 2015). "Although having been considered a more sensitive indicator of renal function in cirrhosis, CysC is influenced by factors independent of GFR which are frequently present in patients with cirrhosis such as elevated CRP or low serum albumin levels." (PMID 26627205, 2015).
Cirrhosis (continued). "Our preliminary results are the first to show a correlation between marker of cardiomyocyte injury (hs-TnT) and circulating AOPPs-albumin in CHC patients with cirrhosis." (PMID 26665009, 2015). "The aim of this study was to evaluate the effect of low dose albumin use for the prevention of PICD related renal impairment following large volume paracentesis in cirrhosis." (PMID 26150850, 2015). "Greater increases in platelets (30,700 vs. 20,100 cells/μl; p = 0.030) and serum albumin (0.3 vs. 0.1 g/dl; p < 0.001) occurred in the cohort with cirrhosis, but both cohorts experienced significant improvements in these two parameters by year 5 on study." (PMID 25788199, 2015). "Albumin infusion improves renal function in cirrhosis; however, mechanisms are incompletely understood." (PMID 26136776, 2015). "Two small RCTs have also demonstrated improved renal function in patients with cirrhosis and hepatorenal syndrome treated with albumin and terlipressin." (PMID 25042164, 2014). "The concentration of albumin in plasma is usually low in patients with cirrhosis and HE, and greater change in albumin levels results in better DTI indices." (PMID 25166619, 2014). "In 1999 Sort and colleagues published the results of a RCT in 126 patients with cirrhosis and spontaneous bacterial peritonitis comparing treatment with intravenous cefotaxime or cefotaxime plus intravenous albumin for plasma volume expansion." (PMID 25042164, 2014). "The diagnostic accuracy of the PVSG, HVAT, HV–HA interval time, HV–PV interval time, ICG-R15, HA, PT % and serum albumin level for detecting cirrhosis (Metavir = F4) was analyzed using a ROC analysis." (PMID 24136649, 2014). "In a recent meta-analysis, the protective effect of albumin on kidney function seemed to be present in patients with cirrhosis." (PMID 25394836, 2014). "Of note, patients with cirrhosis, the group from which most of the evidence regarding the beneficial effect of albumin on kidney function derives, were excluded from the study." (PMID 25394836, 2014). "Eleven Patients with occult HBV infection had higher albumin (ALB), well-differentiated tumors (E-S grades I and II) and a lower risk to develop cirrhosis." (PMID 25229710, 2014). "Classically, serum albumin is normal unless frank cirrhosis has developed; ascitic fluid analysis reveals an elevated serum albumin-ascites gradient (>1.1 g/dL) typical of portal hypertension and demonstrates an elevated total protein level (>2.5 g/dL)." (PMID 24782928, 2014). "In our current animal model, it has been demonstrated that liver fibrosis/early stage cirrhosis is induced with multiple human albumin challenge in 6 weeks, resulting in chronic liver damage." (PMID 23874752, 2013). "Chronic liver disease (liver fibrosis/cirrhosis) was induced in Wistar rats by repeatedly challenging with human serum albumin (HSA), and confirmed by histopathology." (PMID 23874752, 2013). "BCAA treatment increases the ratio of reduced albumin, which in turn decreases oxidative stress by modulating the redox state of albumin in patients with cirrhosis." (PMID 23936183, 2013). "This suggested that the presence of cirrhosis had a dominating influence on the preoperative albumin levels over tumor stage in this specific group of patients." (PMID 23285146, 2012). "In cirrhosis, there is a drop in cell ATP content and mitochondrial dysfunction and a decrease in albumin synthesis." (PMID 23056951, 2012). "The most common albumin indications in our patients were hypovolemia (16.6%), edema (7.2%) and cirrhosis (5.8%)." (PMID 23351175, 2012). "There seems to be important correlations among the necroinflammation as well as the severity of fibrosis/cirrhosis and albumin with serum AFP." (PMID 22675639, 2012). "Albumin and prealbumin are synthesized from liver; therefore, these are poor predictors for nutritional status in patients with cirrhosis." (PMID 23304537, 2012).
Cirrhosis (continued). "The necroinflammation as well as the severity of fibrosis/cirrhosis and a lower serum albumin was shown to be predictor for elevation of serum AFP among chronic HCV with steatosis." (PMID 22675639, 2012). "In a large-scale multivariate analysis, the risk factors and outcome of early recurrence after resection of HCC included cirrhosis, hepatitis B/C, Child-Pugh score, transaminase level, albumin level, chronic active hepatitis." (PMID 21269525, 2011). "Univariate analysis demonstrated that serum albumin, cirrhosis, AFP, and portal vein obstruction (PVO) were prognostic factors of high statistical significance." (PMID 21176210, 2010). "Among the 24 clinicopathological factors analyzed by univariate log-rank analysis, only albumin (ALB) level (P = 0.004), cirrhosis status (P = 0.028) and major vascular invasion (P < 0.001) were identified as poor prognostic factors for OS." (PMID 20925965, 2010). "The serum albumin concentration is usually normal in chronic liver disease, until cirrhosis and significant liver damage develops." (PMID 21194423, 2010). "Patients with advanced cirrhosis (Child B and C) of the liver receiving albumin substitution because of renal compromise were studied using trans-pulmonary thermodilution." (PMID 18752670, 2008). "This study investigated the effects of plasma expansion with hyperoncotic albumin solution and the role of static haemodynamic parameters in predicting volume responsiveness in patients with advanced cirrhosis." (PMID 18752670, 2008). "In contrast to earlier studies we have observed a significant increase in central blood volume and CI after albumin infusion in a substantial proportion of patients with advanced cirrhosis." (PMID 18752670, 2008). "Reversal of serum albumin to globulin ratio and evidence of cirrhosis on abdominal ultrasound were consistent." (PMID 19893665, 2008). "Serum albumin levels were found to be higher in patients with compensated cirrhosis than in other patients." (PMID 19578501, 2008). "Albumin infusion has been shown to improve the response to diuretics in patients with cirrhosis and ascites." (PMID 17134488, 2006). "We found an interaction between the effects of LPS and cirrhosis on the mRNAs of albumin that increased the mRNA level." (PMID 16968543, 2006). "The frequency of cirrhosis, serum bilirubin and albumin and serum activities of alkaline phosphatase, AST and ALT did not significantly differ for patients with PSC or PBC." (PMID 15790420, 2005). "Albumin mitigates these effects, suggesting a direct modulatory role on mitochondrial function and supporting its therapeutic potential in vascular dysfunction in cirrhosis." (PMID 42010744, 2026). "Overall, albumin infusion appears to be a clinically valuable intervention in the management of advanced cirrhosis, but further trials are warranted to clarify its long-term effects, particularly on hepatocellular carcinoma progression and optimal treatment regimens." (PMID 41140983, 2025). "Furthermore, albumin binds toxins, modulates inflammatory responses, and stabilizes endothelial function, all of which are relevant in decompensated cirrhosis and ACLF, where systemic inflammation drives organ failure." (PMID 41140983, 2025). "Cirrhosis not only reduces albumin synthesis but also affects its structure and function." (PMID 40281590, 2025). "Cirrhosis has been shown to impair albumin and prothrombin synthesis." (PMID 40271488, 2025). "This was reinforced by a recent systematic review and meta-analysis involving five randomized controlled trials to suggest an insignificant difference on the use of long-term albumin in improving mortality or other complications of cirrhosis compared to the control groups." (PMID 40143117, 2025). "This aligns with the well-established evidence of the role of albumin in decompensated cirrhosis." (PMID 40591542, 2025).
Cirrhosis (continued). "Studies are required to evaluate albumin utilization in the context of RA and its clinical outcomes in the United States, particularly at the intersection of race and ethnicity, socioeconomic disparities, and cirrhosis." (PMID 41021268, 2025). "Therefore, it is essential to monitor serum albumin levels to stratify the risk of OHE and maintain it to improve the outcomes of older patients with cirrhosis." (PMID 40928524, 2025). "Long-term albumin administration has shown promise in reducing complications of cirrhosis, including infections and renal dysfunction, while short-term use is standard in specific contexts such as large-volume paracentesis, spontaneous bacterial peritonitis, and HRS." (PMID 41140983, 2025). "Dogs with cirrhosis exhibited significantly reduced TP and ALB concentrations." (PMID 40453929, 2025). "Therefore, we utilized real-world data from a large U.S. electronic health record (EHR) database to investigate albumin utilization among patients with cirrhosis and ascites undergoing LVPs." (PMID 41021268, 2025). "Second, information on cirrhosis etiology and concomitant therapies, including alcohol consumption, albumin, and statins, was incompletely available due to the retrospective design, which may influence oxidative stress profiles." (PMID 41300878, 2025). "Therefore, not only does albumin play a role as an indicator of liver function, but the albumin protein itself is known to improve the prognosis of cirrhosis in patients." (PMID 41008815, 2025). "Therefore, we assessed the use of guideline-adherent albumin and outcomes in U.S. patients undergoing LVPs, particularly at the intersection of race, ethnicity, socioeconomic disparities, and cirrhosis." (PMID 41021268, 2025). "However, a systematic review by Kütting et al40 found insufficient evidence to support a mortality benefit from albumin during LVP in HCC-free patients with cirrhosis." (PMID 41021268, 2025). "Study 3 examined the effect of these substances on serum albumin levels in patients with cirrhosis." (PMID 40438352, 2025). "Decreased circulating albumin in cirrhosis causes a lack of sequestration of PGE2, a molecule that normally promotes immunosuppression." (PMID 39402169, 2025). "This superior performance of APP in defining cirrhosis may be attributed to the fact that it combines markers of liver synthetic function (albumin) and portal hypertension (platelet count), two key features typically associated with cirrhosis." (PMID 40550831, 2025). "One patient population that may benefit from albumin administration during septic shock is those with cirrhosis." (PMID 40386509, 2025). "It has been suggested that sarcopenia is a better objective measure of denutrition in patients with cirrhosis as compared to serum (pre‐) albumin, patient weight, or BMI, which may be modified by hepatopathy or ascites." (PMID 40922637, 2025). "While patients with cirrhosis may benefit from albumin administration, the efficacy of albumin for resuscitation in cirrhotic patients with septic shock remains unclear." (PMID 40386509, 2025). "Compared to patients with compensated cirrhosis, patients with decompensated cirrhosis had a significantly different clinical profile, characterized by lower serum albumin (p < 0.001) levels and higher bilirubin (p < 0.001) and creatinine (p = 0.004) concentrations." (PMID 40563298, 2025). "Indeed, several studies have indicated that low albumin levels are associated with more advanced stages of MAFLD, including NASH and cirrhosis." (PMID 40954485, 2025). "Patients with cirrhosis typically exhibit lower levels of albumin due to hepatic fibrosis." (PMID 39199720, 2024). "Notably, even a subtle reduction in serum albumin has been reported to be a predictor for both, clinical decompensation and death among patients with compensated cirrhosis." (PMID 39301299, 2024).